AR (androgen receptor)
Diseases named in the same sentence as AR in open-access papers (continued):
Sharing a sentence is not in itself a finding about the gene and the disease.
prostate carcinoma (continued). "The lack of expression of the prostate-specific genes (AR, NKX3.1, and PSA) at the protein level prompted the investigation of a possible NE prostate cancer phenotype, which was confirmed at the RNA-seq level when 2 NE specific marker (SYP and ENO2) were expressed at RNA-seq." (PMID 36643868, 2022). "To determine if the effect of ITZ on drug resistance was independent of androgen receptor (AR) activity, we investigated if ITZ could reverse DTX resistance in AR-negative ABCB1-overexpressing prostate cancer cell lines." (PMID 35721223, 2022). "Indeed, CAF-derived IL-6 can induce VEGF secretion in established prostate cancer cells via PI3K/AKT signaling, and is independent of AR activation." (PMID 36671452, 2022). "We focused on the AR-positive cell lines VCaP and LNCaP, because other AR-independent or -negative cells such as DU145 or PC3 are so drastically dedifferentiated that they do not reflect early stages of metastasizing prostate cancer." (PMID 36551650, 2022). "Indeed, PC-3 cell line is similar to DU-145 cells, thus being hormone insensitive and showing no AR or PSA (prostate specific antigen) mRNA/protein, in order to reproduce prostate cancer conditions of patients that become resistant to the hormone-therapy." (PMID 33712665, 2021). "As a male reproductive organ, the high level of expression of the AR in cells from the prostate and its disorders, such as benign prostatic hyperplasia (BPH), prostatic intraepithelial neoplasia (PIN) and prostate cancer, is not a surprising experimental result." (PMID 33477370, 2021). "Recent studies revealed that the frequency of AR-negative neuroendocrine prostate cancer (NEPC) and AR-Null and Neuroendocrine-Null Prostate Cancer (Double-Negative PCa, DNPC) is elevated due to the application of potent AR antagonists such as enzalutamide (ENZ) and abiraterone." (PMID 33869227, 2021). "Compared with those in AR-negative prostate cancer cells (IC50 16.0 μM) or those in normal prostate cells (IC50 27.0 μM), ASC-J9 was found to exhibit a decreased IC50 value in AR-positive prostate cancer cells (IC50 6.5 μM)." (PMID 34295247, 2021). "However, AR has been suggested as a key negative factor for the EMT process and metastasis of prostate cancer." (PMID 34743733, 2021). "In prostate cancer cells, ciglitazone and its analogue reduce prostate-specific antigen (PSA) secretion with and without a decrease in the expression of androgen receptor (AR), independent of PPAR-γ activation." (PMID 34631571, 2021). "Prostate cancer cell lines co‐treated with doxorubicin or other drugs only partially target the multidrug resistance proteins in tumours, where a synergistic effect in AR negative PC3 and DU145 cells was observed, but not in the AR positive prostate cancer cells." (PMID 34434533, 2021). "This suggests that NTRK1 and the NGFR might not respond to AR signaling, and the roles of NGF–NGFR or NGF–NTRK1 signaling pathways might differ from that of NGF–CHRM4 signaling in prostate cancer." (PMID 33398073, 2021). "Likewise, the viability of androgen receptor-positive (LNCaP) and androgen receptor-negative (DU-145 and PC3) human prostate cancer cells was significantly decreased by the treatment with irisin (10–100 nM)." (PMID 34071869, 2021). "Taken together, our data showed that both AR regulated PMEPA1 isoform e and TGF-β responsive isoforms c and d could not suppress cell growth of hormone responsive prostate cancer cells and interrupt androgen signaling." (PMID 32064040, 2020). "Interestingly, miR-31-5p was the miRNA showing the most negative correlation with AR (Pearson score −0.43 and p-value = 0.0026) and concomitant positive correlation with ESR1 (Pearson score 0.49 and p-value = 0.0004) in our cohort of prostate cancer tissues." (PMID 32041153, 2020). "However, it only inhibited prostate cancer proliferation in LNCaP and C4-2 cells, which are expressing AR but not in DU145 cells, which do not express AR." (PMID 33321809, 2020).
prostate carcinoma (continued). "Additionally, it was further revealed that PMEPA1-b isoform as an AR signaling inhibitor and PMEPA1-a has no impact on AR signaling in prostate cancer cells." (PMID 32064040, 2020). "In addition, knockdown of AR did not completely abolished the effect of SP-2509 treatment in LNCaP cells, which suggests an important AR-independent role of LSD1 in prostate cancer progression." (PMID 31901895, 2020). "At present, its role(s) in prostate cancer has not been fully investigated, although our previous study demonstrated that TSPX could inhibit the transactivation of androgen receptor (AR) on its target genes." (PMID 30863497, 2019). "Besides PC-3 cells, D3P-21 also recognises lung cancer cell lines, e.g. A549 and H460, whereas the breast cancer cell line MCF-7 and the androgen receptor and PSA positive prostate cancer cell line LNCaP were not bound." (PMID 30899039, 2019). "To explore if SPRY2 could mediate resistance to ADT independent of PTEN status, we investigated the levels of AR, PTEN and SPRY2 in a panel of prostate cancer cell lines (Fig EV1K)." (PMID 29540470, 2018). "Prostate carcinoma cell line PC3, which does not express AR, served as negative control." (PMID 29731997, 2018). "However, SRA knockdown also exerts these effects in DU145 cells, which are AR-negative, suggesting that SRA also exerts AR-independent effects to modulate prostate cancer progression." (PMID 30238005, 2018). "For these reasons we evaluated AR expression in UCM 1037-treated LNCaP and 22Rv1 cells and what we found was a remarkable down regulation of AR protein levels, which has never been observed before in melatonin-treated prostate cancer cells." (PMID 29783631, 2018). "As seen in prostate cancer cells, non-androgens, such as epidermal growth factor (EGF), could increase AR transcriptional activity in bladder cancer cells, which was blocked by AR antagonists." (PMID 28241422, 2017). "An alternative mechanism of AR activation independent of androgen binding includes its phosphorylation via kinases [e.g., epidermal growth factor receptor (EGFR)] in, for instance, prostate cancer cells." (PMID 28241422, 2017). "The lack of synergy among AR, HOXC6 and NKX2-2 suggests that the three master TFs may indeed compete for a common epigenetic co-factor to inhibit miRNA expression in prostate cancer." (PMID 28397780, 2017). "AKT1-mediated phosphorylation of EZH2 allows its interaction with androgen receptor promoting the expression of androgen receptor-target genes in the absence of androgens further supporting the involvement of EZH2 in the development and progression of castrate resistant prostate cancer." (PMID 27793053, 2016). "Moreover, contrary to PSEBC-TSTA, PCA3-3STA remained active in androgen receptor (AR)-negative prostate cancer cells (PC-3 and DU145) while it was silent in AR-positive breast cancer cells (CAMA-1)." (PMID 26594800, 2016). "One hypothesis that could explain that prostate cancer invariably escapes from ADT and androgen targeted therapy (ATT) would be the existence of a subpopulation of prostate CSCs that are AR negative and therefore insensitive to androgen deprivation." (PMID 27378372, 2016). "While enzalutamide inhibited the proliferation of prostate cancer cell lines with a 5-fold difference in IC50 values between AR-positive and -negative prostate cancer cell lines, it inhibited TNBC cell lines at comparable concentrations regardless of the AR expression." (PMID 27918430, 2016).
prostate carcinoma (continued). "Therefore, TACC2 does not necessarily involve in AR signaling and other factors can be important in the regulation of TACC2 expression in the breast carcinoma, different from the prostate carcinoma." (PMID 27333920, 2016). "Finally, THCA-A reduces cell viability in different prostate carcinoma cell (PCC) lines, both androgen-receptor positive (LNCaP, 22RV1) and androgen-receptor negative (DU-145, PC-3)." (PMID 28861488, 2016). "Using prostate cancer cell lines of distinct genetic background, DACH1 was shown to inhibit proliferation in vitro and tumor growth in vivo of both AR negative cancer cell (PC-3) and castration resistant AR positive cell (C4-2 and 22RV-1)." (PMID 26682253, 2015). "Moreover, CsA was shown to inhibit the growth of both androgen-sensitive and androgen receptor (AR)-negative prostate cancer lines, while FK506 inhibited only AR-dependent growth but failed to do in AR-negative cells." (PMID 25638160, 2015). "Moreover, the results showed that mRNA level of EZH2, AR and SRC3 are upregulated in prostate cancer compared to normal prostate tissues and this correlates positively with Gleason score, PSA levels and clinical stages." (PMID 25535400, 2014). "Interestingly, both ERα and NEAT1 signalling were refractory to AR inhibitors and the lack of AR or ERβ, thus indicating a functional specialization of the ERα-NEAT1 axis for prostate cancer progression." (PMID 25415230, 2014). "In prostate cancer evidence support the link between the activation of RTKs, like the insulin-like growth factor, keratinocyte growth factor, EGFR or HER2, and the transactivation of the AR in the absence of androgens." (PMID 24779793, 2014). "In the present study, LNCaP, which is an androgen receptor-positive and androgen-responsive prostate cancer cell line derived from lymph node metastasis, and DU145, which is an androgen receptor-negative prostate cancer cell line derived from brain metastasis, were investigated." (PMID 25371717, 2014). "Although multiple mechanisms appear to contribute to castrate-resistant prostate cancer (CRPC), it has been hypothesized that one origin might be immature, AR negative, tumor-propagating cells, similar to multipotent progenitors." (PMID 22022528, 2011). "To date, this has not been possible in prostate cancer, although recent work suggests the imprinting of the TMPRSS2-ERG, PTEN, and androgen receptor configurational status may be suitable." (PMID 22096655, 2011). "In vitro hydroxyflutmamide induced rapid activation of ras/MAP kinase pathway in human prostate cancer DU145 cells (which lack the androgen receptor) as well as in CWR22 and PC-3AR2 androgen receptor positive cells lines, indicating that the activation did not require androgen receptor." (PMID 18986533, 2008). "The data from gene expression profiles shows that expression of AR RNA is absent in 30 to 40 % of prostate cancer samples (GEO accession: GSE1431) and the proportion of prostate cancers not expressing AR is increased in metastatic prostate cancer (GEO accession:GSE3325)." (PMID 16774685, 2006). "Prostate cancer cells treated with antiandrogenic drugs can develop castration-resistant prostate cancer (CRPC), a condition where tumor cells acquire the mechanisms for survival and proliferation independent of androgen receptor (AR) signaling, while androgen-dependent cells undergo apoptosis." (PMID 41614823, 2025). "Analysis of multiple prostate cancer cohorts, including our in-house tissue collection (Tongji) and publicly available datasets from TCGA, GEO, and MSKCC, consistently showed a significant negative correlation between AR expression and both LTFe and LTF expression." (PMID 40082405, 2025).
prostate carcinoma (continued). "Although the potential mechanism by which VNPP433-3β facilitates AR degradation is not completely clear, a recent study has provided evidence that VNPP433-3β serves as a molecular glue that effectively degrades AR and AR-V7, thereby inhibiting oncogenic signaling pathways in prostate cancer cells." (PMID 40866949, 2025). "Having demonstrated that Thio-2 inhibits AR signaling and the growth of prostate cancer models independent of BAG-1 isoform function, we investigated whether its mechanism of action may be mediated through the AR NTD as it has previously been shown to inhibit AR NTD transactivation." (PMID 38412481, 2024). "Neuroendocrine prostate cancer (NEPC) is a highly aggressive form of prostate cancer (PCa), which is commonly characterized by typical neuroendocrine (NE) markers such as ENO2, SYP, and CHGA, but no or low levels of androgen receptor (AR) and AR-regulated genes." (PMID 39505875, 2024). "Therefore, patients with prostate cancer receiving ADT/ARIs harbor a spectrum of tumor cells, including those with AR expression but a temporarily or permanently inactive AR-signaling axis and those lacking AR altogether." (PMID 36561929, 2022). "However, unlike LnCap prostate cancer cells with nuclear specific AR distribution, both GBM cell lines cultured in vitro showed cytosol-enriched subcellular localization of AR which is in contrast with the nuclear dominant localization of GBM patients’ specimens based on IHC staining." (PMID 34094902, 2021). "It is noteworthy to mention that prostate cancer has been reported to be driven by ERα, AR, and non-genomic estrogen signaling pathways mediated by orphan receptors like GPR30 and ERRα and, hence, phytoestrogens have been shown to have a beneficial role in prostate cancer." (PMID 35187021, 2021). "Compared with the other subtypes of prostate cancer, NEPC expresses specific neuroendocrine markers including synaptophysin (SYP), chromogranin A (CgA), and neuronal‐specific enolase (NSE), with concurrent absence of androgen receptor (AR) and prostate‐specific antigen (PSA)." (PMID 33009820, 2021). "In addition, AR is a TF regulating KLK3 transcript levels and, interestingly, AR-negative prostate cancer PC3 cell line does not present a promoter annotation for KLK3 gene, hence indicating the absence of ChIP-seq signal supporting the presence of a promoter for KLK3 gene." (PMID 33186463, 2020). "Consequently, nonsteroidal AR antagonists have been developed, and some of them, such as flutamide (2a) and bicalutamide (BIC, 3), are in clinical use to treat prostate cancer." (PMID 32759847, 2020). "Moreover, the prostate cancer cells used in this study do not express detectable levels of the PR and as such, any ARCC-4 induced signaling or proliferation effects can be solely attributed to AR degradation and not PR-A or PR-B suppression." (PMID 30271980, 2018). "This differs from what has been recently described in other prostate cancer models of lineage plasticity in which EZH2 inhibition resulted in re-expression of the AR26,28, possibly due to an earlier more “plastic” disease state in those models where AR was not completely absent prior to therapy." (PMID 29921838, 2018). "Transcriptional activation by the ARv567es AR isoform occurs via a DNA looping mechanism that involves interaction with the transcription factor MED1 (part of the mediator complex involved in transcriptional initiation), and within castration-resistant but not hormone-responsive prostate cancer." (PMID 28382513, 2017). "Therefore, DNAH8 copy number amplification, in concert with or independent of AR, could promote DNAH8 expression in advanced prostate cancer." (PMID 27363033, 2016).
prostate carcinoma (continued). "While majority of prostate cancers are initially androgen dependent and respond to androgen ablation therapy, most patients eventually recur with more aggressive castration-resistant prostate cancer (CRPC) where AR signaling is reactivated even in the absence of androgen stimulation." (PMID 25605250, 2015). "The impact of such SRs for prostate cancer biology is currently not understood, but a reasonable hypothesis is that they develop – like the TMPRSS2:ERG gene fusion – as a consequence of highly active androgen receptor (AR) signaling." (PMID 24684958, 2014). "Because the majority of the AR variants identified thus far do not harbor the hinge domain, AR splicing represents a key mechanism by which the AR protein escapes SPOP-mediated polyubiquitination and proteasome degradation, thereby contributing to prostate cancer pathogenesis." (PMID 24508459, 2014). "Culig and colleagues demonstrated that, in human prostate cancer cells, various growth factors including insulin-like growth factor 1 (IGF-I), keratinocyte growth factor (KGF), and epidermal growth factor (EGF) directly activate the AR in the absence of androgens." (PMID 23896594, 2013). "However, by eradicating androgen-dependent prostate cancer cells, ADT may actually promote disease progression by activating normally quiescent cancer stem cells to repopulate the tumor with AR negative, androgen-independent cells." (PMID 24212771, 2011). "Therefore, by downregulating AR through a nontranscriptional mechanism, 25-OCH3-PPD could eliminate prostate cancer cells and/or make them more sensitive to chemotherapeutic drugs or radiation." (PMID 18253123, 2008). "However, AR expression is not correlated with PSA expression, which suggests that PSA expression in late-stage prostate cancers may be driven by mechanisms that are independent of the AR." (PMID 16859559, 2006). "In addition, transcriptome sequencing of ETS-fusion-negative prostate cancer revealed genetic rearrangements involving RAF-kinase family members, namely SLC45A3-BRAF and ESRP1-RAF1, recurrent in about 2% of advanced PCa cases, the former one being AR-regulated." (PMID 33634124, 2021). "For example, in a subgroup of patients with castrate resistant prostate cancer, tumors with ERG-rearrangement but no detectable ERG protein expression may indicate a non-functional AR pathway, suggesting that these patients may not benefit from therapy directed against the AR pathway." (PMID 31741711, 2019). "Because TRAMP mice lacking expression of androgen receptor are thought to be models for a very advanced stage with neuroendocrine cancer cells and independent from androgen receptor, the findings using TRAMP mice might be compatible with prostate cancer patients in only the late stage." (PMID 30736371, 2019).